CD109 (CD109 molecule)
Diseases named in the same sentence as CD109 in open-access papers (continued):
Sharing a sentence is not in itself a finding about the gene and the disease.
tumor (continued). "In the present study, we first verified that the tumor-promoting effects of CD109 knockdown in HUVEC were mainly mediated by paracrine IL-8." (PMID 27121053, 2016). "The aptamer S3, identified by cell-SELEX approach, has good affinity for CD109, and can recognize its target in peripheral blood, tumor spheres, and clinical tissue specimens." (PMID 27419372, 2016). "The immunohistochemistry staining of CD109 expression in a tissue microarray of 142 HCC patients showed that, in addition to tumor cells being positive for CD109 staining in a few patients, expression was mainly observed on tumor microvessels." (PMID 27121053, 2016). "In this study, we found that reduced expression of CD109 on tumor vessels was correlated with large tumor size, microvascular invasion, advanced tumor stage, and poor survival after curative resection of HCC." (PMID 27121053, 2016). "QPCR and western blot were used to detect the expression levels of CD109 in 5-8F cells and 5-8F tumor spheres." (PMID 27419372, 2016). "HUVEC with different CD109 expression were co-implanted with HCCLM3 or HepG2 cells in nude mice to investigate the effect of CD109 expression on tumor growth and metastasis." (PMID 27121053, 2016). "In conclusion, CD109 expression on tumor vessels serves as a prognostic marker for HCC patients after curative resection." (PMID 27121053, 2016). "Cell lysates of tumor tissues were analyzed by western blotting with anti-FLAG pAb, anti-CD109-C-9 and -CD109-11H3 mAb, which confirmed high CD109 expression in HEK293-FLAG-hCD109 tumor tissues compared with that in HEK293-VC tumor tissues." (PMID 24400073, 2014). "Compared with other tumor markers, the half-life of CD109 is longer than those of SCC antigen and CYFRA (2.2 h and 1.5 h, respectively), and is shorter than those of CEA and CA19-9 (1.5 days and 12 h, respectively)." (PMID 24400073, 2014). "In the present study, we investigated the availability of CD109 as a tumor marker, using mCD109-TG mice and HEK293 xenografted mice." (PMID 24400073, 2014). "In this study, we investigated CD109 as a novel serum tumor marker using transgenic mice that overexpress mouse CD109 (mCD109-TG mice) and tumor xenografted mice inoculated with human CD109 (hCD109)-overexpressing HEK293 cells." (PMID 24400073, 2014). "Concentrations of secreted CD109 decreased notably by 17 h after tumor resection, and became undetectable 48 h after resection." (PMID 24400073, 2014). "Proteomics study indicates that CD109 is released from some tumor cell lines and related to TGF-β signaling in vitro." (PMID 24400073, 2014). "Seventeen hours after the operation, the concentration of CD109 was reduced to one-seventh to one-eighth, indicating that half-life of tumor-secreted CD109 is about 5.86±0.17 h." (PMID 24400073, 2014). "Assuming that CD109 has a monophasic elimination pattern, the half-life of tumor-secreted CD109 calculated from these results was 5.86±0.17 h, which indicates that tumor-secreted CD109 is rapidly washed out from the serum after tumor resection." (PMID 24400073, 2014). "Since immortalized cancer cell lines only serve as surrogates for human tumors, we examined CD109 expression in a series of human PDAC tumor and normal pancreas tissue sections by IHC." (PMID 25635161, 2014). "Forty-two days after the xenograft, tumor resections were performed as described in Materials and Methods, and serum samples were analyzed for CD109 by western blotting and ELISA." (PMID 24400073, 2014). "CD109 is a glycosylphosphatidylinositol-anchored cell surface glycoprotein and is one of 12 endothelial markers over-expressed in tumor endothelial cells." (PMID 25506915, 2014). "CECs expressing CD109, a marker of tumor endothelial cells, as well as other CEC and CEP subtypes, were investigated by six-color flow cytometry." (PMID 24069296, 2013).
tumor (continued). "The only gene that showed a higher methylation at more advanced tumor stages was CD109, which was methylated at a rate of 56%, 76%, and 86% at stages I, II and (III+IV), respectively." (PMID 19750230, 2009). "Moreover, another study has shown that patient-derived CD109 positive cells are highly enriched with clonogenic, tumour-initiating, and radiation-resistant properties, and the silencing of CD109 resulted in the significant inhibition of these phenotypes." (PMID 40227788, 2025). "Therefore, next the expression levels of CD44 and CD109 were also determined in the tumour specimens from these patients at different cut-off values." (PMID 40227788, 2025). "On the other hand, CD109 overexpression has been reported in some cancers and CD109 expression has been associated with chemoresistance by upregulation of EGFR, and alteration of the tumour microenvironment." (PMID 40227788, 2025). "Indeed, cross-talk between different members of the HER family and with CD44 or CD109 has been shown to influence tumour cell behaviour and progression." (PMID 40227788, 2025). "CD44 is a putative cancer stem cell biomarker and may interact with EGFR, CD109, and EGFRvIII to facilitate the tumour progression and resistance to therapies." (PMID 40227788, 2025). "Delineating the functional significance of CD109 dysregulation in SCC will involve defining the molecular mechanisms by which CD109 may regulate SCC tumor progression." (PMID 40317079, 2025). "In these conditions, CD109 could contribute to immune dysfunction by promoting a suppressive tumor microenvironment, characterized by impaired cytotoxic lymphocyte activity, cytokine imbalances, and chronic inflammation." (PMID 39990858, 2024). "Therefore, CD109’s impact on TEC not only affects tumor advancement and prognosis but also serves as a significant regulator of the local immune environment." (PMID 39990858, 2024). "Given the interplay between EMT and inflammation in cancer, where pro-inflammatory cytokines like TGF-β and NF-κB drive EMT, CD109’s capacity to modulate these processes and cancer progression suggests that CD109 promotes SCC tumor progression through these pathways." (PMID 39990858, 2024). "In TNBC, CD109 may modulate key inflammatory and tumor-promoting pathways, such as TGF-β, EGFR, and GP130, which are all implicated in TNBC progression." (PMID 39990858, 2024). "As a critical regulator of the GP130/IL-6/STAT3 pathway, CD109 may act as a crucial link between chronic inflammation and tumor development." (PMID 39990858, 2024). "CD109 has been reported to promote tumor malignancy by regulating various signaling pathways." (PMID 37373457, 2023). "To investigate the role of CD109 in tumor initiation and progression in vivo, we analyzed the development of intracranial xenografts derived from control and CD109-silenced GSCs using 4 different sets of GSCs initially enriched with either the MES- or PN-like signature." (PMID 33986188, 2021). "In addition, CD109 silencing completely inhibited the growth of the MES-like BT13 tumors that consist of a large primary tumor as well as the growth of the PN-like BT18 and ZH305 models that grow very diffusively." (PMID 33986188, 2021). "CD109 silencing significantly impaired tumor growth in all studied models." (PMID 33986188, 2021). "Tumor resection seemed to be an important event for reducing the serum CD109 level." (PMID 33565282, 2021). "Paradoxical roles of TGFβ signaling can be either promote or suppress tumor formation, suggesting that CD109 regulates EMT in a cellular context manner and that also highlights the crucial role of CD109-YAP/TAZ signaling pathway in regulating EMT and cancer stemness." (PMID 33375719, 2020). "Moreover, the formation of tumorspheres, which refers to the self-renewal ability of stem-like tumor cells, significantly decreased in CD109-knockdown A549 and CL-LM cells." (PMID 33375719, 2020).
tumor (continued). "Likewise, CD109 suppression resulted in the downregulations of tumor invasiveness and tumorsphere formation were restored by the ectopic expression of YAP." (PMID 33375719, 2020). "Finally, we also calculated odds ratios of the association between CD109, TGF-β/P-Smad2, clinical stage and tumor grade in OSCC." (PMID 31695056, 2019). "Furthermore, to confirm that these two antibodies were directed against CD109, BxPC-3 tumour lysates were immunoprecipitated with the two novel antibodies, transferred by Western blot and then probed with a commercial anti-CD109 antibody." (PMID 29731998, 2018). "In the current study, we sought to determine whether hBM-MSCs regulate the malignant properties of SCC cells, and whether CD109 plays a role in mediating hBM-MSC's effects on tumor progression." (PMID 29221155, 2017). "Therefore, in the context in which TGF-β acts as a tumor suppressor, CD109 would inhibit the tumor suppressor function of TGF-β, endowing hBM-MSCs with ability to favor tumor growth and progression." (PMID 29221155, 2017). "This is consistent with the notion that TGF-β functions as a tumor promoter in late stage cancer and indicates that CD109 may partially mediate the anti-metastatic activity of hBM-MSC-CM." (PMID 29221155, 2017). "This is the first report suggesting that CD109 may account for the tumor inhibitory activity of hBM-MSCs and linking CD109 to the inhibition of TGF-β-induced EMT and stemness." (PMID 29221155, 2017). "It is speculated that reduced expression of CD109 on TEC may facilitate tumor growth and metastasis in HCC patients." (PMID 27121053, 2016). "Furthermore, we investigated the correlation between CD109 expression on tumor vessels and the prognosis after curative resection of HCC." (PMID 27121053, 2016). "Co-implantation with CD109 knockdown HUVEC accelerated tumor growth and metastasis in mice models." (PMID 27121053, 2016). "Interleukin-8 (IL-8) was a key tumor-promoting factor secreted from CD109 knockdown HUVEC." (PMID 27121053, 2016). "Tumor volume and serum CD109 concentrations were analyzed over time." (PMID 24400073, 2014). "As CD109 is reportedly cleaved by furin and its soluble form is secreted into culture medium in vitro, we hypothesized that CD109 could serve as a tumor marker in vivo." (PMID 24400073, 2014). "Next, we evaluated whether tumor-secreted CD109 in the serum of HEK293-FLAG-hCD109 xenografted mice decreases after tumor resection." (PMID 24400073, 2014). "Taken together, our results indicate that CD109 is a potential tumor marker." (PMID 24400073, 2014). "The half-life of tumor-secreted CD109 was about 5.86±0.17 h." (PMID 24400073, 2014). "Interestingly, it has been reported that CD109 is one of 12 endothelial markers over-expressed in tumor endothelial cells." (PMID 25506915, 2014). "Concentrations of tumor-secreted CD109 increased proportionally as tumors enlarged." (PMID 24400073, 2014). "Our findings suggest that CD109 is a potential tumor marker." (PMID 24400073, 2014). "Therefore, CD109 is a new candidate among serum tumor markers for premalignant and malignant lesions." (PMID 24400073, 2014). "CD109, a glycosylphosphatidylinositol-anchored cell surface glycoprotein, is highly expressed in several solid tumors and is one of 12 endothelial markers more expressed in tumor than normal endothelial cells." (PMID 24069296, 2013). "In our project CD109 was found to have a 1.9× fold change between high and low vascularity tumours." (PMID 22311740, 2012). "Furthermore, we investigated whether CD109 affects IL-6-induced tumorigenicity in SCC cells using an in vitro tumor spheroid formation assay." (PMID 40317079, 2025). "Moreover, mice that received CD109-KO cells remained tumor free for an additional 6 months." (PMID 35954339, 2022). "Furthermore, we found that 180 kDa soluble CD109, which is also secreted as a component of exosomes, could be detected in the sera of tumor xenografted mice." (PMID 33565282, 2021).
tumor (continued). "However, further analyses of the patient samples revealed that CD109 expression significantly associated with increasingly phosphorylated STAT3 (p-STAT3, Tyr705) (P = 0.004) and higher number of Ki-67–positive, proliferating tumor cells (P = 0.027)." (PMID 33986188, 2021). "Notably, CD109 is highly expressed in well-to-moderate SCC relative to poorly differentiated SCC tumors, suggesting that CD109 might play an essential role in tumor progression." (PMID 31695056, 2019). "Though expressed on several types of tumor cells, CD109 may be a potential TEC marker." (PMID 27121053, 2016). "Therefore, CD109 may be a good marker for monitoring tumor progression and response to surgical treatment, which proportionally increases with tumor volume and rapidly decreases after tumor resection." (PMID 24400073, 2014). "In addition, serum CD109 immediately decreased after tumor resections in this study." (PMID 24400073, 2014). "Thus, detailed investigation of CD109 concentration in serum of normal individuals and cancer patients is required, and specific tools for detecting tumor-derived CD109 by eliminating normal tissue-derived CD109 would be quite useful for application of CD109 as a tumor marker." (PMID 24400073, 2014). "Paradoxically, however, CD109 is upregulated in SCC and we and others found that it strongly promotes SCC tumor progression via EGFR pathway activation." (PMID 40317079, 2025). "For example, at the cut-off value of ≥5% of tumour cells with positive immunostaining, CD44 expression was detected in 95% of the cases examined, and 16% of the cases were CD109 positive." (PMID 40227788, 2025). "Given that KRASG12D PDAC‐derived CD109+EVs deliver circPNIT to neurons and trigger axonogenesis‐induced PNI, we sought to determine the targeted engagement of circPNIT in the primary tumor tissue generated by KRASG12D PDAC." (PMID 39488792, 2024). "In this regard, inhibiting CD109 is known to reduce EGFR signaling, suppress the Akt/mTOR pathway, and increase tumor cell sensitivity to EGFR inhibitors, highlighting its potential as a promising therapeutic target in lung cancer." (PMID 39990858, 2024). "One article showed expression of the unusual markers CD105, 2E4B4, 58B1, W5C4, and CD109 in both the SW982 line and in primary tumor samples from patients." (PMID 37173919, 2023). "Immunohistochemical staining was performed to visualise the expression of BMP1, CD109, LTBP1, PSAP, and NPC2 in human control colonic tissue, primary tumour, and liver metastasis." (PMID 36134447, 2022). "In the present study, we demonstrate that the loss of CD109 reduces stemness and tumorigenicity in vitro and abrogates tumor initiation and the metastatic ability of vulvar SCC cells in vivo, indicating an oncogenic role for CD109 in vulvar SCC." (PMID 35954339, 2022). "In terms of tumor stage, differential expression of NEGR1, NTNG1, XPNPEP2, CD109, and PRND had statistical significance in all tumor stage groups." (PMID 34737762, 2021). "None of the studied markers were detected in the brains of mice implanted with the CD109-silenced BT13 cells, confirming the complete abolishment of tumor initiation/formation." (PMID 33986188, 2021). "Consistent results were observed in CL-LM cells in which inhibition of CD109 attenuated EMT-related gene expressions and tumor mobility." (PMID 33375719, 2020). "Functionally, CD109 expression was crucial for EMT gene expressions, tumor invasiveness, and cancer stemness properties." (PMID 33375719, 2020). "These in vitro findings are in line with our clinical data from 52 OSCC patient samples which suggest that the expression of CD109 inversely correlates with TGF-β signalling and tumor grades." (PMID 31695056, 2019). "Further validations using 52 human oral SCC samples show that CD109 levels inversely correlate with TGF-β signalling and tumor grade." (PMID 31695056, 2019).
tumor (continued). "To explore the clinical relevance of CD109 in human oral SCC, we assessed the expression of CD109, TGF-β and phosphoSmad2 (P-Smad2) in 52 human oral SCC (OSCC) tumor samples using tissue microarray immunohistochemistry." (PMID 31695056, 2019). "To confirm this observation, we assessed the correlation between CD109, TGF-β and P-Smad2 in relation to tumor clinical stages and pathological grades." (PMID 31695056, 2019). "Overexpression of PlGF, CD109, CD137, and CD276 have been identified in ECs of tumor tissues in comparison to ECs of non-tumor tissues." (PMID 31555593, 2019). "CD109 is a GPI-anchored cell surface glycoprotein that is expressed in a wide variety of cell types including skin cells, mesenchymal stem cells and tumor cells." (PMID 31695056, 2019). "Thus, JAK/STAT3 signaling might mediate the effects of CD109 in tumor growth and metastasis." (PMID 29625613, 2018). "In conclusion, CD109 expression on tumor vessels is a potential prognostic marker for HCC, and its reduced expression on TEC promoted tumor progression by paracrine IL-8." (PMID 27121053, 2016). "In the present study, we found that CD109 knockdown inhibited tube-forming capability of HUVEC, but significantly promoted tumor growth and metastasis in a paracrine manner." (PMID 27121053, 2016). "At least four genes (CD109, CHD5, LGR6, and ICAM5) displayed a different level of methylation, depending on the tumor location." (PMID 19750230, 2009). "For example, at the same cut-off value of ≥5% of tumour cells with positive immunostaining, the expression of wtEGFR was accompanied by co-expression with HER2 (35%), HER4 (30%), EGFRvIII, CD44 (44%), CD109 (4%), and HER2/HER4 (29%), respectively." (PMID 40227788, 2025). "CD109 interacts with EGFR to activate the Akt/mTOR pathway, driving tumor growth." (PMID 39990858, 2024). "CD109 induces EGFR-mediated STAT3 phosphorylation, which supports SCC cell migration, proliferation, and the cancer stem cell phenotype, highlighting its role in enhancing tumor aggressiveness and inflammation." (PMID 39990858, 2024). "It is plausible that CD109 could influence BMP-mediated inflammatory responses, cytokine production, and immune cell infiltration, thereby contributing to the tumor’s inflammatory and metastatic potential." (PMID 39990858, 2024). "CD109 may amplify this process, as it interacts with EGFR to activate the Akt/mTOR pathway, driving tumor growth." (PMID 39990858, 2024). "CD109 is highly expressed in TNBC, correlating with chemotherapeutic resistance and poor outcomes, and may influence tumor progression and inflammation, highlighting the need for further research." (PMID 39990858, 2024). "Contrary to its typical role as a negative regulator of TGF-β signaling, CD109 may actually promote TGF-β action, as has been recently reported that CD109 is involved in the activation of latent TGF-β to active TGF-β, enhancing tumor invasion and inflammation." (PMID 39990858, 2024). "In addition, several studies have shown that CD109 is highly expressed in both NPC cell lines and tumor tissues." (PMID 36968209, 2023). "BMP1, CD109, and LTBP1 showed a gradual and clear increase of expression from the control tissues to the metastatic tissues, with preferential cytoplasmic staining in the tumour tissue, being more intense in metastasis." (PMID 36134447, 2022). "Our observations reveal that the microglial component was a minority in the tumor compartment and CD109 was exclusively expressed by the tumor cells and not by the host microglia." (PMID 33986188, 2021). "We also found a significant reduction in the levels of tumor promoter GPs at the end of 4th week during 4-week intermittent fasting (POLK, CD109, CAMP, NIFK, SRGN), and 1 week after 4-week intermittent fasting (CAMP, PLAC1) compared with the levels before 4-week intermittent fasting." (PMID 33110154, 2020).